ORM1 (orosomucoid 1)
Diseases named in the same sentence as ORM1 in open-access papers (continued):
Sharing a sentence is not in itself a finding about the gene and the disease.
diabetes (3 papers, 2014 to 2023). "RNA and whole exon sequencing of tumors from 13 patients who developed ICI-induced diabetes mellitus (ICI-DM) showed significant overexpression of ORM1, PLG, G6PC and a missense mutation in NLRC5." (PMID 37497220, 2023).
gastric cancer (3 papers, 2013 to 2022). A primary or metastatic malignant neoplasm involving the stomach. "ORM1 plays an important role in acute phase reaction and inflammatory response, and is highly expressed in plasma of multiple cancers, including gastric cancer." (PMID 36505781, 2022).
Hypertension (3 papers, 2014 to 2026). The presence of chronic increased pressure in the systemic arterial system. "Proportional correlations of CKD duration-PAI1 levels and sCr-lipocalin 2 levels but inverse correlations of orosomucoid 1-hypertension duration and SDMA-DBP were evident in cases." (PMID 41596619, 2026).
liver cancer (3 papers, 2022 to 2024). An epithelial or non-epithelial malignant neoplasm that arises from the liver. "Our current study cannot prove that salivary ORM1 is a specific marker of liver cancer, but our screening and diagnosis of liver cancer mainly focus on patients with chronic liver disease caused by hepatitis B virus infection." (PMID 36096917, 2022). "In this study, ORM1 was found to be a potential salivary marker for HBV-associated liver cancer." (PMID 36096917, 2022). "Subsequent studies can also explore ORM1 influence on the prognosis of liver cancer and its mechanism further." (PMID 36096917, 2022). "This may be partially attributed to the control group because ORM1 is differentially expressed in acute hepatitis, liver cirrhosis, liver failure, and liver cancer." (PMID 35765957, 2022). "Theoretically, viral hepatitis is an example of a chronic stimulus that may alter ORM1 expression and thus play an important role in the transition from chronic hepatitis to hepatic cancer." (PMID 35765957, 2022). "The results indicated that ORM1 was downregulated in hepatic cancer cells compared to that in non-cancerous cells, although it seems that ORM1 had a higher level in the stroma of HCC tissues." (PMID 35765957, 2022). "Although ORM1 expression was lower in hepatic cancer cells than in non-cancerous ones, vascular invasive tumor cells had higher levels of ORM1." (PMID 35765957, 2022). "AFP and ORM1 showed strong staining in liver cancer tissues, and comparing the staining index of liver cancer tissue and normal adjacent tissue of the same patient, the expression of AFP and ORM1 in liver cancer tissue was significantly higher than that normal tissue (AFP: p = 0.035,ORM1:p < 0.001)." (PMID 36096917, 2022). "Nonetheless, a consensus has not been reached on whether ORM1 expression is up- or down-regulated in liver cancer compared to non-tumor tissues with different ORM1 expression profiles reported in the previous studies." (PMID 35765957, 2022). "The results indicated that ORM1 was significantly downregulated in the hepatic cancer cells compared with the levels in non-cancerous cells; however, it was upregulated in microvascular invasion samples, especially in the cancer embolus, compared with that in the surrounding tumor cells." (PMID 35765957, 2022). "We found orosomucoid 1(ORM1) had significantly higher expression in saliva of HCC patients compared with non-HCC groups (p < 0.001) and the expression of ORM1 in liver cancer tissues was significantly higher than that in adjacent normal tissues (p < 0.001)." (PMID 36096917, 2022).
non-small cell lung carcinoma (3 papers, 2016 to 2022). A group of at least three distinct histological types of lung cancer, including non-small cell squamous cell carcinoma, adenocarcinoma, and large cell carcinoma. "In non-small cell lung cancer patients treated with docetaxel, the response rate for high baseline ORM1 group was 14%, while for low ORM1 group it was 44%." (PMID 27021626, 2016).
ovarian cancer (3 papers, 2019 to 2022). A primary or metastatic malignant neoplasm involving the ovary. "The previous studies have shown that ORM1 expression serves as a predictor of therapeutic effects in ovarian cancer and lymphoma." (PMID 35765957, 2022).
schizophrenia (3 papers, 2020 to 2023). A major psychotic disorder characterized by abnormalities in the perception or expression of reality. "Reduced angiotensinogen (AGT) in males, and increased alpha-1 acid glycoprotein (ORM1) in females were the most significant sex-specific protein features in patients with schizophrenia." (PMID 34741130, 2022).
chronic heart failure (2 papers, 2014 to 2021). "Recent proteomic studies have shown that urinary and serum alpha-1-acid glycoprotein-1 (AGP1), also known as ORM1, have been proposed as prognostic biomarkers for inflammatory diseases such as chronic heart failure, some types of cancer, and lately for PA." (PMID 34804057, 2021). "Relationship between urinary ORM1/Cr level and chronic heart failure." (PMID 25215505, 2014).
depression (2 papers, 2020 to 2024). "Additionally, there exist a multitude of significant genes that vary between sexes and are linked to depression, like ORM1, ORM2, RNF32, SLC25A5, Thbs1, and Cadps2 etc., manifesting sex-specific impacts on depression risk." (PMID 38903903, 2024).
heart failure (2 papers, 2014 to 2018). Inability of the heart to pump blood at an adequate rate to meet tissue metabolic requirements. "IL6 stimulates angiotensinogen, serum amyloid P, fibrinogen, and orosomucoid-1 and inhibits transthyretin signifying men who developed heart failure had increased IL6 activity, whereas women with heart failure had decreased IL6 activity." (PMID 30132266, 2018). "The correlation indicated by the Spearman test is 0.499, suggesting that the level of ORM1 was markedly elevated in urine as heart failure worsened." (PMID 25215505, 2014).
hepatic diseases (2 papers, 2022). "ORM1 is predominantly synthesized in the liver, hepatic diseases may have more influence on its expression, ORM1 can be induced in liver injury and activate the liver cell cycle to achieve liver regeneration." (PMID 36096917, 2022). "As ORM1 is predominantly synthesized in the liver, hepatic diseases may have more influence on its expression." (PMID 35765957, 2022).
Hepatitis (2 papers, 2012 to 2022). Inflammation of the liver. "Previous studies have demonstrated that ORM1 has the capacity to inhibit TNFα activity and protects mice from TNFα -induced lethality or hepatitis caused by TNFα and galactosamine." (PMID 22916107, 2012).
lung squamous cell carcinoma (2 papers, 2022 to 2025). "The m7G immune-related genes FGA, CSF3R, and ORM1 increase the survival risk in patients with lung squamous cell carcinoma, whereas NTS exerts a protective effect." (PMID 40098956, 2025).
pericarditis (2 papers, 2017 to 2020). An inflammatory process affecting the pericardium. "The levels of LRG1 were increased in patients with lymphadenopathy, pneumonia, and pleuritis (p < 0.05); the levels of ORM1 were increased in patients with pericarditis and pneumonia (p < 0.05)." (PMID 33013889, 2020).
pulmonary TB (2 papers, 2020 to 2022). "The main sources of ORM1 are alveolar macrophages and type II pneumocytes at the early stage of pulmonary TB." (PMID 33292280, 2020).
squamous cell carcinoma (2 papers, 2012 to 2025). A carcinoma arising from squamous epithelial cells. "Moreover, increased levels of ORM1 have been reported in the sera of patients with different malignant diseases, including squamous cell carcinoma of head and neck." (PMID 22888844, 2012).
steatosis (2 papers, 2022 to 2025). Increased lipid within the cytoplasm of cells. "According to ELISA and western blot (30 urine samples, normalized to urine creatinine), ceruloplasmin (ROC 0.78, p = 0.034) and ORM1 (ROC 0.87, p = 0.005) showed moderate diagnostic accuracy in distinguishing mild steatosis from healthy controls." (PMID 35741222, 2022). "Ceruloplasmin (ROC 0.79, p = 0.028) and ORM1 (ROC 0.81, p = 0.019) also showed moderate diagnostic accuracy in distinguishing severe steatosis from mild steatosis." (PMID 35741222, 2022). "ORM1 and ceruloplasmin are potential biomarkers to distinguish mild steatosis from healthy controls, and severe steatosis from mild steatosis, in patients with MAFLD." (PMID 35741222, 2022). "Numerically, the alpha-1-acid glycoprotein 1 (ORM1) from cluster three (up-regulated panel) was 4.5-fold (Un-log2) higher in mild steatosis, and 7.1-fold higher in severe steatosis." (PMID 35741222, 2022). "Proteins such as orosomucoid-1 (ORM1) and ceruloplasmin have been identified as potential biomarkers capable of distinguishing mild steatosis from healthy individuals and differentiating severe steatosis from mild cases in MASLD patients." (PMID 40427524, 2025).
ameloblastic carcinoma (1 paper, 2016). A rare, cytologically malignant ameloblastoma that may metastasize. "Since orosomucoid-1 belongs to a group of acute-phase proteins and has many functions in health and disease, we identified and analyzed orosomucoid-1 expression in ameloblastoma variants and ameloblastic carcinoma using western blot and immunohistochemical techniques." (PMID 27386438, 2016).
ameloblastoma (1 paper, 2016). The most common odontogenic tumor, arising from the epithelial component of the embryonic tooth and usually affecting the molar-ramus region of the mandible or maxilla. "Orosomucoid-1 may play an important role in the behavior of ameloblastomas and influence the biology and development of the variants of this tumor." (PMID 27386438, 2016). "Although we now have some information on the role of ORM1 in ameloblastoma and AC, many questions remain to be resolved." (PMID 27386438, 2016). "Suggesting the specific function of ORM1 in ameloblastoma is difficult due to the multiple roles for ORM1 that have been described." (PMID 27386438, 2016). "This leads us to consider a possible immunomodulatory function of ORM1 in the biological behavior of ameloblastomas." (PMID 27386438, 2016). "Finally, although ORM1 is known to have many functions, immunological and functional experiments such as proliferation, migration and invasion assays or gene silencing and over-expression assays will be necessary to better elucidate the role of ORM1 in ameloblastomas." (PMID 27386438, 2016). "Thus far, background ORM1 expression has not been found in any variant of ameloblastomas and has only been found in odontogenic myxomas, but the nature of these tumors is different; ameloblastoma is an epithelial tumor, whereas odontogenic myxoma is a mesenchymal tumor." (PMID 27386438, 2016).
anemia (1 paper, 2025). A reduction in the number of red blood cells, the amount of hemoglobin, and/or the volume of packed red blood cells. "IVW methods with FDR correction revealed significant associations of ORM1 with phenotypes of blindness, low vision, and acute posthemorrhagic anemia (FDR < 0.05)." (PMID 40299486, 2025).
Anorexia (1 paper, 2024). Lack of desire to eat (loss of appetite). "Another acute-phase protein, ORM1, is a potential contributor to anorexia through its role in the excessive activation of hypothalamic leptin receptor signaling." (PMID 39727925, 2024). "In the present study, both Apcs and Orm1 were induced, suggesting the activation of systemic inflammatory and anorexia-inducing pathways." (PMID 39727925, 2024).
arenavirus infection (1 paper, 2018). "Little is known about the function of Orm1 during arenavirus infection; however, it is classified as an acute phase plasma protein." (PMID 29724035, 2018).
asthma (1 paper, 2011). "Review of previous T1D genome-wide association results revealed that four (human leucocyte antigen (HLA), gasdermin B/ORM1 (Saccharomyces cerevisiae)-like/gasdermin B/, GSDMB/ORMDL3/GSDMA and IL2RB) of ten loci recently reported to be associated with asthma were associated with T1D (p≤0.005)." (PMID 22069270, 2011).
atopic dermatitis (1 paper, 2024). "However, acknowledging the ongoing importance of LC in atopic dermatitis, additional research is needed to elucidate how significant genetic factors (Trp73, Orm-1, Chi3l3, Ccl20, AnXa1, Alox5, Ccr1, and Fcεr1a, etc.)identified in our study may interact with LC function and the disease process." (PMID 38834629, 2024).
babesiosis (1 paper, 2023). Babesiosis refers to a condition caused by microscopic parasites that infect the red blood cells. "Other identified proteins that differentiated uncomplicated from complicated babesiosis were various complement cascade components (CFI, CFP, C2, SERPING1, C8G), extracellular matrix components (TGFBI), acute phase proteins (ORM1, ITIH2, ITIH4, FGA, TF, RBP4) and lipoproteins (apoE)." (PMID 37353646, 2023).
cervical disease (1 paper, 2022). "In the future, the ORM1 function research in cervical disease is warranted." (PMID 36498728, 2022). "The role of ORM1 as a biomarker of cervical disease is reported for the first time in our study." (PMID 36498728, 2022).
cystitis (1 paper, 2021). Inflammation of the urinary bladder. "In the present paper ORM1 levels were normalized and HPX values were restored after administration of AA in animals with CYP-induced cystitis." (PMID 34072606, 2021).
endocarditis (1 paper, 2024). Inflammation of the endocardium. "Study of the Orm1-Hp couple may be useful for the diagnosis of endocarditis." (PMID 39546466, 2024).
epilepsy (1 paper, 2021). A brain disorder characterized by episodes of abnormally increased neuronal discharge resulting in transient episodes of sensory or motor neurological dysfunction, or psychic dysfunction. "This study indicated that ORM1 may play important role in epilepsy." (PMID 34555062, 2021). "The study showed that decreasing the ORM1 expression may be a possible mechanism for the aggravation of BBB damage, while the disruption of BBB may underlie the occurrence of seizures and epilepsy." (PMID 34555062, 2021).
hemorrhagic stroke (1 paper, 2025). A stroke caused by a bleed on the brain. "ORM1 has been identified as one of the differentially expressed genes in hypertensive cerebral hemorrhage, suggesting its potential involvement in the pathophysiology of hemorrhagic stroke." (PMID 40672462, 2025).
Hepatic hemangioma (1 paper, 2023). A congenital vascular malformation in the liver composed of masses of blood vessels that are atypical or irregular in arrangement and size. "We further investigated the predictive role of ORM1 in CRLM by detecting ORM1 expression levels in 10 blood samples from patients with benign liver diseases (hepatic hemangioma and FNH) or malignant tumors (HCC and ICC) using ELISA." (PMID 37640741, 2023). "Serum ORM1 levels were significantly higher in CRLM patients than those in patients with benign liver diseases (hepatic hemangioma or FNH), HCC, or ICC." (PMID 37640741, 2023).
hepatitis B (1 paper, 2022). "We are the first to report that salivary orosomucoid 1 as a biomarker of hepatitis B associated hepatocellular carcinoma." (PMID 36096917, 2022). "In a word, salivary ORM1 as a new biomarker of hepatitis B associated hepatocellular carcinoma, combination of salivary ORM1 and AFP as an improved diagnostic tool for hepatocellular carcinoma." (PMID 36096917, 2022).
Insulin resistance (1 paper, 2016). Increased resistance towards insulin, that is, diminished effectiveness of insulin in reducing blood glucose levels. "Secondly, these cytokines do not appear to contribute to the reported insulin resistance induced by ORM1 in porcine adipose tissue in vitro as an increase in the abundance of these inflammatory cytokines would be predicted during an insulin resistant state." (PMID 27087941, 2016). "The present data suggest that adiponectin may not have a role in countering ORM1 induced insulin resistance in neonatal pig adipose tissue in vitro since ORM1 did not alter adiponectin mRNA abundance." (PMID 27087941, 2016).
kidney damage (1 paper, 2023). "The role of ORM1 in inflammatory cascades, and the fact that glomerular inflammation is a distinct pathologic hallmark of LN, support ORM1 as a useful biomarker for early detection for LN and for the presumption of kidney damage." (PMID 37744355, 2023).
leukemia (1 paper, 2018). A malignant (clonal) hematologic disorder, involving hematopoietic stem cells and characterized by the presence of primitive or atypical myeloid or lymphoid cells in the bone marrow and the blood. "For instance, ORM1 and ORM2 are already shown to be involved in AML, LTF is a high-profile gene whose role in AML needs further investigation, and S100A12 is shown to be involved in similar subtypes of leukemia, such as ALL, and is suggested to be involved in AML as well." (PMID 29589558, 2018).
myocardial infarction (1 paper, 2016). Gross necrosis of the myocardium, as a result of interruption of the blood supply to the area, as in coronary thrombosis. "Additionally, in a study on human myocardial infarction, human polymorphonuclear cells were shown to synthesize and release ORM1, suggesting that ORM1 provides endogenous inhibitory feedback in response to excessive inflammation." (PMID 27386438, 2016).
odontogenic tumors (1 paper, 2016). "However, whether orosomucoid-1 is expressed in other odontogenic tumors remains unknown." (PMID 27386438, 2016).
ovarian tumors (1 paper, 2018). "The significance of APOC2, APOC4, ORM1, SERPINA1, and SERPINA10 in differential diagnosis of ovarian tumors was not confirmed." (PMID 30065196, 2018).
psoriasis (1 paper, 2014). An autoimmune condition characterized by red, well-delineated plaques with silvery scales that are usually on the extensor surfaces and scalp. "Interestingly, of these, only ORM1 has been previously associated with psoriasis, where ORM1 was increased in the plasma of psoriatic patients." (PMID 25097465, 2014).
renal fibrosis (1 paper, 2021). A final common manifestation of a wide variety of chronic kidney diseases characterized by glomerulosclerosis and tubulointerstitial fibrosis. "In triple (ORM1-3) knockout mice (unlike humans, mice have 3 ORM genes), enhanced inflammation and a greater susceptibility to renal fibrosis in the unilateral ureteral obstruction and acute ischemia-reperfusion models have been reported." (PMID 34912827, 2021).
staphylococcus aureus infection (1 paper, 2013). An infectious process in which the bacteria Staphylococcus aureus is present. "Finally, the same degree of hepatic down-regulation of the pig ORM1 gene was shown after experimental Staphylococcus aureus infection, accompanied by a more than 10 fold increase in pig MAP expression." (PMID 23844161, 2013). "Also looking at the liver response, experimental Staphylococcus aureus infection resulted in an approximate 4 fold reduction in ORM1 expression at 30–48 hours after challenge, concomitantly with a pigMAP gene induction of around 20 fold and a haptoglobin gene expression fold change around two." (PMID 23844161, 2013).
systemic lupus erythematosus (1 paper, 2023). An autoimmune multi-organ disease typically associated with vasculopathy and autoantibody production. "In the previous study, urine levels of ORM1 and SERPINC1 were elevated in newly diagnosed LN patients compared with healthy controls (HC) and systemic lupus erythematosus (SLE) patients without nephritis." (PMID 37744355, 2023).
triple-negative breast carcinoma (1 paper, 2022). An invasive breast carcinoma which is negative for expression of estrogen receptor (ER), progesterone receptor (PR), and human epidermal growth factor receptor 2 (HER2). "For CoCNV, some genes in the PMI network gene set can classify patients into groups with significantly different survival probability by their single gene CNV, such as CTLA4, ORM1, and RASAL3 in triple negative breast cancer." (PMID 35610556, 2022).